USP53 (ubiquitin specific peptidase 53)
Diseases named in the same sentence as USP53 in open-access papers (continued):
Sharing a sentence is not in itself a finding about the gene and the disease.
Cholestatic liver disease (4 papers, 2020 to 2025). "USP53 was shown to be associated with pediatric cholestatic liver disease, obese, cantu syndrome, and mice progressive hearing loss." (PMID 33973730, 2021). "We report a pediatric case of cholestatic liver disease associated with two novel compound heterozygous variants in the USP53 gene: a truncating c.1219A>T (p.Lys407*) variant inherited from the father and a maternally inherited gross deletion involving exons 13–19." (PMID 41356217, 2025).
esophageal cancer (4 papers, 2023 to 2024). A primary or metastatic malignant neoplasm involving the esophagus. "After activation by H3K27 acetylation, USP53 inhibits the progression of esophageal cancer through the AMPK pathway." (PMID 37894400, 2023).
lung adenocarcinoma (4 papers, 2022 to 2023). A carcinoma that arises from the lung and is characterized by the presence of malignant glandular epithelial cells. "USP53 is lowly expressed in lung adenocarcinoma, and USP53 deubiquitinates FKBP51, which thereby inhibits tumor growth in lung adenocarcinoma." (PMID 37795365, 2023). "Lung adenocarcinoma cells are regulated by USP53, which deubiquitinates FKBP51, dephosphorylates AKT1, and controls glycolysis and apoptosis." (PMID 37894400, 2023). "USP53 induced the apoptosis of lung adenocarcinoma cells through deubiquitination of FKBP51." (PMID 35654790, 2022). "Besides, USP53 could also induce cell apoptosis in lung adenocarcinoma cells through deubiquitinating FKBP51." (PMID 35654790, 2022). "USP53 (Ubiquitin specific peptidase 53) inhibits the initiation and progression of renal cell carcinoma by inhibiting activation of the nuclear factor κB (NF‐κB) pathway; it promotes apoptosis and inhibits glycolysis in lung adenocarcinoma through FKBP51‐AKT1 signaling." (PMID 35486664, 2022).
Cantu syndrome (3 papers, 2021 to 2024). "This was not only similar to the skeletal changes associated with aberrant USP53 expression in Cantu syndrome but also consistent with the down-regulation of USP53 expression in the bone marrow of osteoporosis patients." (PMID 39300775, 2024).
cervical cancer (3 papers, 2021 to 2024). A primary or metastatic malignant neoplasm involving the cervix. "In addition, it has been found that USP53 can regulate the radiosensitivity of cervical cancer." (PMID 37894400, 2023).
deafness (3 papers, 2021 to 2025). An inherited or acquired condition characterized by the complete loss of the ability to hear from one or both ears. "USP53 encodes a protein of uncertain function and USP53 deficiency causes deafness in mice." (PMID 34681012, 2021). "Since USP53 colocalizes and interacts with the tight junction scaffolding proteins TJP1 and TJP2 in a mouse-deafness model, it has been suggested that USP53 is a component of the tight junction complex." (PMID 34681012, 2021).
lung carcinoma (3 papers, 2024 to 2025). "Studies have shown that USP53 expression was down-regulated in lung cancer, which was significantly lower than that in normal adjacent tissues and was related to tumor size, smoking status, and lymph node metastasis." (PMID 39300775, 2024). "There was a statistical difference in the survival rate of patients with high and low expression of USP53, which was a prognostic protective factor for lung cancer." (PMID 39300775, 2024). "In another study, Western Blot, MTT, transcriptome sequencing, transwell, and ubiquitination experiments demonstrated that USP53 can regulate the expression of ZEB1 in lung cancer cells (A549 and H1975), thereby inhibiting EMT and further reducing cell migration, invasion, and cisplatin tolerance." (PMID 39300775, 2024).
osteoporosis (2 papers, 2021 to 2024). A condition of reduced bone mass, with decreased cortical thickness and a decrease in the number and size of the trabeculae of cancellous bone (but normal chemical composition), resulting in increased fracture incidence. "Furthermore, the roles of USP53 in osteoporosis were examined in an OVX mouse model to induce estrogen deficiency-related osteoporosis." (PMID 33664230, 2021). "Finally, USP53 expression was decreased in patients with osteoporosis and in a mouse model of estrogen deficiency-induced osteoporosis." (PMID 33664230, 2021). "Taken together, these results demonstrated that USP53 expression was downregulated in patients and mice with osteoporosis." (PMID 33664230, 2021). "The results showed that USP53 expression in BMSCs from patients with osteoporosis was downregulated compared with that in normal controls." (PMID 33664230, 2021). "Notably, USP53 expression in patients with osteoporosis was downregulated compared with that in normal controls." (PMID 33664230, 2021). "However, our findings are limited because we did not examine whether USP53 mutation/deletion was present in patients with osteoporosis." (PMID 33664230, 2021).
renal carcinoma (2 papers, 2021 to 2025). A carcinoma arising from the epithelium of the renal parenchyma or the renal pelvis. "We also tested the expression of USP53 in human normal renal epithelial cells and four renal cancer cell lines (RCC) by RT‐PCR and western blot." (PMID 33973730, 2021). "The results showed that USP53 knockdown significantly promoted the migration and invasion of renal cancer cells Caki‐1 and 786‐O cells." (PMID 33973730, 2021). "Therefore, it can be explained that the gene USP53 can inhibit the migration and invasion of renal cancer cells." (PMID 33973730, 2021). "Additionally, the degree of malignancy of renal cancer cells is correlated with the expression level of the USP53 gene, indicating that USP53 could be a viable target for gene therapy of renal carcinoma." (PMID 40225869, 2025).
schizophrenia (2 papers, 2023 to 2024). A major psychotic disorder characterized by abnormalities in the perception or expression of reality. "Cysteine residues in USP53 mambo mutations were found to correspond to those in patients with schizophrenia." (PMID 39300775, 2024). "USP53 has been implicated in several pathways related to schizophrenia, such as ubiquitin processing, folate metabolism, and tight junction physiology." (PMID 39300775, 2024). "We identified a novel missense variant in USP53 associated with autosomal recessive transmission of severe psychosis/schizophrenia in a multiplex consanguineous family." (PMID 37895270, 2023). "If confirmed, USP53 appears to be one of the few Mendelian variants potentially causal to a common-appearing mental disorder that is a rare genetic form of schizophrenia." (PMID 37895270, 2023). "No USP53 variants have been previously reported specifically associated with schizophrenia." (PMID 37895270, 2023).
benign recurrent intrahepatic cholestasis (1 paper, 2025). Benign recurrent intrahepatic cholestasis (BRIC) is a hereditary liver disorder characterized by intermittent episodes of intrahepatic cholestasis, generally without progression to chronic liver damage. "Clinically, USP53-related disease often presents with a milder, benign recurrent intrahepatic cholestasis (BRIC)-like phenotype, featuring episodic jaundice and pruritus with slow disease progression." (PMID 41356217, 2025).
bipolar disorder (1 paper, 2023). A disorder of the brain that causes unusual shifts in mood, energy, activity levels and the ability to carry out day-to-day tasks. "In another instance, a heterozygous SNV USP53, chr4:120190897, c.1340A>G, p.(Glu447Gly)was one among 17 other candidates identified in a multiplex family with nine individuals suffering from bipolar disorder." (PMID 37895270, 2023). "A heterozygous USP53 frameshift variant 4:120190846:CTAAGT:C was identified in a study of de novo variation in 97 trios of Ashkenazi Jewish descent with early onset bipolar disorder and without a family history of bipolar disorder (“simplex”)." (PMID 37895270, 2023).
breast tumors (1 paper, 2023). "To assess whether USP53 promotes the growth of breast tumors in vivo, we constructed an MDA-MB-231 cell line with stable shUSP53 expression and verified the USP53 expression levels through Western blotting." (PMID 37894400, 2023).
cervical squamous cell carcinoma (1 paper, 2023). A squamous cell carcinoma arising from the cervical epithelium. "Additionally, by combining with DDB2, USP53 improved the radiotherapy sensitivity of cervical squamous cell carcinoma cells." (PMID 37894400, 2023).
colorectal cancer (1 paper, 2024). A primary or metastatic malignant neoplasm that affects the colon or rectum. "The role of USP53 in the diagnosis and treatment of colorectal cancer deserves further exploration." (PMID 39300775, 2024). "CCK8 and clonal formation experiments suggested that overexpression of USP53 can inhibit the proliferation and clonogenesis of HCT116 colorectal cancer cells in vitro." (PMID 39300775, 2024).
COVID-19 (1 paper, 2025). A disease caused by infection with severe acute respiratory syndrome coronavirus 2. "In influenza, UBE2S, USP53, and TIMM10 were observed in this category, while in COVID-19, UBE2T, UBE2C, DTL, MT-ND2, UCHL1, and UBA52 were implicated." (PMID 41020849, 2025).
developmental delay (1 paper, 2023). "A patient with the variant USP53 c.951delT; p.Phe317fs was found segregating the phenotype of speech and developmental delay along with itching and benign recurrent intrahepatic cholestasis." (PMID 37895270, 2023).
diabetes (1 paper, 2022). "The USP53 genes has a greater involvement in cholestatic liver disease and the IGF2 proteins are widely known as the diabetes associated protein and can control the insulin secretion in β-cells during fasting." (PMID 35277538, 2022).
dilated cardiomyopathy (1 paper, 2020). Cardiomyopathy which is characterized by dilation and contractile dysfunction of the left and right ventricles. "Importantly, three of these genes were validated as ‘diagnostic’ genes given the strong evidence supporting causality derived from our data repository (CAP2-dilated cardiomyopathy, ITFG2-intellectual disability and USP53-liver cholestasis)." (PMID 33083013, 2020).
familial intrahepatic cholestasis (1 paper, 2025). An instance of intrahepatic cholestasis that is caused by an inherited modification of the individual's genome. "Conspicuously, mutations within the USP domain of USP53 cause progressive familial intrahepatic cholestasis." (PMID 39587316, 2025). "However, we were intrigued by recent reports that identified loss or biallelic mutations in USP53 as the cause for progressive familial intrahepatic cholestasis, a hereditary liver disorder in children." (PMID 39587316, 2025).
hemangioma (1 paper, 2021). A benign vascular lesion characterized by the formation of capillary-sized or cavernous vascular channels. "It is possible that biallelic mutations in the USP53 gene disrupt the formation of dense connections between endothelial cells, which leads to the development of hemangiomas." (PMID 34681012, 2021).
Hypocalcemia (1 paper, 2025). An abnormally decreased calcium concentration in the blood. "USP53, the gene responsible for PFIC7, was found to be related to hearing loss and hypocalcemia." (PMID 39984942, 2025).
kidney cancer (1 paper, 2021). Primary or metastatic malignant neoplasm involving the kidney. "USP53 belongs to USPs family, but there have been no reports of its involvement in cancer, so we want to explore the effect of USP53 on the development of kidney cancer." (PMID 33973730, 2021). "The results showed that compared with normal kidney cells, USP53 is significantly lower expressed in kidney cancer cells." (PMID 33973730, 2021). "Compared with normal kidney cells, USP53 is significantly lower expressed in kidney cancer cells." (PMID 33973730, 2021).
mental disorder (1 paper, 2023). A disease that has its basis in the disruption of mental process. "No prior data addressed the involvement of USP53 in the CNS or in glutamatergic neurotransmission, psychosis, or any mental disorder." (PMID 37895270, 2023).
Obesity (1 paper, 2023). Accumulation of substantial excess body fat. "Since USP2, 7, 15, 19, and 20 stimulate either adipogenesis or lipid synthesis, they are likely to cause obesity, while USP53 might be restorative for obesity." (PMID 36834633, 2023). "It has been suggested that USP53, in contrast to USP2, 7, 15, 19, and 20, may have beneficial effects on obesity." (PMID 36834633, 2023).
psychosis (1 paper, 2023). "A murine Usp53 mutant (mambo, mbo) was reported previously with a serine substitution at Cys228 (GRCm39; c.123,751,372), precisely where the human variant associated with psychosis has an arginine substitution." (PMID 37895270, 2023). "Therefore, defining the USP53 interactome must be a priority to understand the biology of USP53 as related to psychosis." (PMID 37895270, 2023).
visual disorders (1 paper, 2016). "It is also worth noting that Usp45, Usp53 and Usp54 did show layer specificity, as they were mainly expressed in the photoreceptors (PhR inner segment, ONL and OPL), suggesting a specific role for these genes in photoreceptors and underscoring their role as potential candidates for visual disorders." (PMID 26934049, 2016).
tumor (13 papers, 2021 to 2025). "These patterns reinforce RCC1’s classification as an oncogene and USP53’s potential role as a tumor suppressor, further validating RCC1’s therapeutic relevance." (PMID 40163507, 2025). "USP19, USP44, USP46, and USP53 has been revealed as potential tumor suppressor in KIRC in the previous study." (PMID 37259026, 2023). "We performed transwell assays after transfection with siControl or siUSP53 in MDA-MB-231 cells and the vector control or USP53 plasmid in MDA-MB-468 cells to evaluate the possible impact of USP53 on tumor migration and invasion in vitro." (PMID 37894400, 2023). "In this study, we explored the role of USP53 as a tumor suppressor in HCC via the deubiquitination of cytochrome c (CYCS), which triggered the mitochondria apoptosis pathway." (PMID 35654790, 2022). "To summarize, we identified USP53 as a tumor suppressor as well as a therapeutic target in HCC, providing novel insights into its pivotal role in cell apoptosis." (PMID 35654790, 2022). "USP53 overexpression significantly decreased the growth rate and the tumor volume, which implied lower proliferative ability." (PMID 35654790, 2022). "USP53 mRNA levels were significantly reduced in the tumor tissues compared to the adjacent liver tissues." (PMID 35654790, 2022). "USP53 showed a significant decrease at both mRNA and protein level in the tumor tissues compared with the adjacent tissue." (PMID 35654790, 2022). "Caki‐1 tumor cells after USP53 knockdown were transplanted subcutaneously on the right side of the scapula of nude mice." (PMID 33973730, 2021). "In‐depth analysis of TCGA database clinical sample pathological diagnosis grading information show analysis of USP53 expression is the correlation with tumor malignancy." (PMID 33973730, 2021). "A tumor xenograft experiment was used to verify the effect of the proliferation of ccRCC after USP53 knockdown." (PMID 33973730, 2021). "USP53 expression was downregulated in ccRCC tissues and USP53 expression was significantly negatively correlated with the tumor progression and clinical prognosis." (PMID 33973730, 2021). "Next, the ability of tumor formation under in vivo conditions after USP53 knockdown was studied by subcutaneous tumor formation in nude mice." (PMID 33973730, 2021). "We weigh isolated tumors and make statistics and we found the tumor weight after USP53 knockdown is much larger than shCtrl." (PMID 33973730, 2021). "Finally, we further studied the role and mechanism of USP53 in vivo by constructing the transplanted tumor model of MCF-7 cell nude mice." (PMID 39044157, 2024). "Moreover, animal experiments demonstrated that USP53 overexpression inhibited tumor growth in nude mice." (PMID 39300775, 2024). "Recovering the expression of the tumor suppressor, such as USP19, USP44, and USP53, also might reach the tumor-inhibited effect for this type of patient." (PMID 37259026, 2023). "With the gradual decrease in the expression of E-cadherin, USP53, which was upregulated in tumour cell, could promote apoptosis through FKBP51-AKT1 signalling." (PMID 37817210, 2023). "Here, we show that the deubiquitinase USP53 contributes to tumor growth and metastasis in TNBC." (PMID 37894400, 2023). "The in-situ expression of USP53 in the tumor tissues was verified by IHC." (PMID 35654790, 2022). "USP53 mediate NF‐κB signaling pathway is also used for verification in other tumor contexts." (PMID 33973730, 2021). "Further understanding of USP53 regulation in ccRCC may assist the development of new therapeutic strategies for targeted tumor therapy." (PMID 33973730, 2021). "We showed that USP53 is negatively correlated with ccRCC tumor progression and survival prognosis." (PMID 33973730, 2021). "The results show that knockdown of USP53 significantly promotes tumor growth of ccRCC in vivo." (PMID 33973730, 2021).
tumor (continued). "Their representative genes include the tumor suppressor genes LHPP, VGLL4, USP53, and CLDN6, which have been reported to play significant anti-tumor functions in a variety of cancer types." (PMID 38831454, 2024). "Among annotations of differentially enriched regions, we discovered that tumor suppressor genes such as LHPP, VGLL4, USP53, and CLDN6 had increased H3K9ac signals in their promoter regions under the metformin condition." (PMID 38831454, 2024). "The overexpression of USP53 in TNBC promotes the deubiquitination of CRKL and tumor growth and metastasis in TNBC." (PMID 37894400, 2023). "USP53 deubiquitinates FKBP51, which in turn dephosphorylates AKT1 and ultimately inhibits tumor growth in LUAD." (PMID 36969062, 2023). "To explore the expression of USP53 in TNBC, we measured USP53 protein expression and mRNA levels individually in five paired tumor and adjacent normal tissues of TNBC patients." (PMID 37894400, 2023). "In summary, we found that USP53 can deubiquitinate CRKL, thus regulating tumor proliferation, metastasis, and sensitivity to chemotherapy in TNBC." (PMID 37894400, 2023). "Overall, we discovered that USP53 deubiquitinates CRKL, encourages tumor development and metastasis, and reduces chemosensitivity in TNBC." (PMID 37894400, 2023). "To verify these results, we analyzed USP53 mRNA and protein expression levels in 33 and eight pairs of HCC tumor and peri-tumor tissues using RT-qPCR, IHC, and WB assays." (PMID 35654790, 2022). "In order to assess the role of USP53 in the development of HCC, we evaluated its expression levels in 371 HCC samples and 50 peri-tumor samples using the RNA-seq data from TCGA-LIHC database." (PMID 35654790, 2022). "In‐depth analysis of the clinical significance of USP53 expression and tumor stages, ccRCC samples were divided into I‐II, III, and IV stages, the results showed that as tumor grade increases, USP53 expression decreases." (PMID 33973730, 2021). "In addition, USP53 overexpression significantly decreased the percentage of Ki-67+ proliferating cells and increased that of TUNEL + apoptotic cells in the tumor tissues compared to the control." (PMID 35654790, 2022). "We compared four GSE databases of ccRCC and found that USP53 expression in tumor tissue was significantly lower than normal tissue and we also got the same result in TCGA‐KIRC database." (PMID 33973730, 2021).